CD40LG (CD40 ligand)
Diseases named in the same sentence as CD40LG in open-access papers (continued):
Sharing a sentence is not in itself a finding about the gene and the disease.
cancer (394 papers, 1973 to 2026). A tumor composed of atypical neoplastic, often pleomorphic cells that invade other tissues. "Utilizing Cox regression analysis to evaluate overall survival, we observed a favorable prognosis associated with elevated CD40LG expression across nine cancer types, namely LUAD, HNSC, SARC, and CHOL." (PMID 41048996, 2025). "In most cancers, as classical immunostimulators, CD40LG and TNFSF14 were negatively associated with SLC3A2." (PMID 35992269, 2022). "Since soluble CD40 expression would suppress CD40LG+ T cells and contribute to immune escape mechanisms, it is critical to explore this splice variant in cancer cells." (PMID 32256143, 2020). "Boxplot analysis shows that the expression of CD40LG is significantly increased in paracancerous tissues compared to cancer tissues (P<0.0001), corroborating our previous bioinformatics analysis findings." (PMID 41048996, 2025). "Cox regression analysis showed a significant relationship between higher CD40LG expression and improved prognosis across eight cancer types, namely LUAD, HNSC, LIHC, and CHOL." (PMID 41048996, 2025). "There were also significant interactions between insulin-expressing cancer cells and immune cells, namely CD40LG (INS+FOSlow, INS+) − CD40 (B cell) and APP (INS+) − TREM2 + TYROBP (macrophage)." (PMID 40438247, 2025). "The soluble form of CD40 ligand (sCD40L) has garnered increasing attention as a potential biomarker in cancer diagnosis and progression." (PMID 39120299, 2024). "The pre-CRT levels of soluble CD40-ligand (sCD40L) and the post-CRT levels of chemokine ligand-5 (CCL5) were associated with the malignant tumor behaviors of depth and invasion, and higher post-CRT IL6 was associated with a poor response." (PMID 38534922, 2024). "Cancer cells modulate the expression and secretion of several anti-proliferative molecules on DBMSCs, including, CD40LG, CXCL9, IL9R, IL-15, TNFSF13B, IL-9, IL-17, and CXCL1." (PMID 39768220, 2024). "As per the QPCR array data, Rapamycin is believed to induce apoptosis in cancer cells by altering the components of the extrinsic (CD40LG, DAPK1, LTA, TNFRSF21) and intrinsic (BIRC5, BNIP3) apoptotic pathways as well as the TP73 upstream modulator." (PMID 38276004, 2024). "This inherent heterogeneity and variability underscore the need for novel and reliable biomarkers like soluble CD40 ligand (sCD40L) in cancer research and clinical practice." (PMID 39120299, 2024). "The multifaceted role of CD40 ligand (CD40L) and its soluble form (sCD40L) in cancer biology underscores their significance as potential biomarkers and therapeutic targets." (PMID 39120299, 2024). "These genes are related to the immune system and tumors: GNG7 is related to PI3K-Akt and Chemokine, FKBP4 is related to Estrogen, and IGF2BP1 is related to miRNA in the cancer pathway, and CD40LG is related to the NF-kappa B and T cell receptors." (PMID 36249053, 2022). "On the other hand, expressing CD40 ligand (CD40L) to the CD40 receptor on APCs leads to cancer cell apoptosis and Th-1 immune reaction, followed by cytotoxic T cell activation and nullified immunosuppression." (PMID 36755812, 2022). "Decreased expression of CD40LG on the T cells of cancer patients indicates an impaired immune response." (PMID 35127491, 2021). "Several clinical studies have found the changed biomarkers of platelet activation, such as soluble P-selectin, CD40 ligand, and β-thromboglobulin in cancer." (PMID 28977972, 2017). "We explored targeted delivery of CD40 ligand to the cancer cell-surface as a therapeutic option for treatment of malignancies." (PMID 24741998, 2014). "CD40LG exhibits different prognostic effects in different types of cancer, which may reflect tissue-specific immune environments." (PMID 41048996, 2025). "Although elevated serum levels of soluble CD40 ligand (sCD40L) were reported in patients with cancer, the importance of high sCD40L levels in clinical oncology remains unknown." (PMID 37892436, 2023).
cancer (continued). "Moreover, cancer patients also present with increased expression levels of platelet-derived substances in the circulation, including CD40 ligand (CD40L), P-selectin, tissue factor (TF) and platelet-derived microparticles (PMPs)." (PMID 37170255, 2023). "After identifying the anti-tumoral role of CD40/CD40LG in pan-cancer analysis, we next explored whether any cancer type(s) may alter CD40 in tumorigenesis." (PMID 34758832, 2021). "Granules of active platelets secrete the CD40 ligand (CD40L) so as to induce cancer cell apoptosis." (PMID 34790823, 2021). "LncRNA TSPOAP1-AS1 showed a significant correlation with the immune-related gene BTLA in 15 kinds of cancers, with a strong correlation in PAAD and CHOL (|r| > 0.8), and the other mainly significant immune genes included CD28 (in 18 types of cancer) and CD40LG (in 14 types of cancer)." (PMID 34195204, 2021). "In carcinomas, the nature of CD40 ligand shapes the outcome of CD40 ligation." (PMID 31941968, 2020). "One of the cancer treatment strategies is to use CD40-ligand/interleukin-2 vaccines." (PMID 25117071, 2014). "Both high CD40 and low–moderate CD40 ligand expression—potentially conducive to CD40 agonist therapy—was most frequent in ovarian (33%) and pancreatic (24%) cancer." (PMID 41182434, 2025). "A positive correlation was observed between the CD40LG IHC score and the proportion of CD8+T cells in the total region, cancer region, and stromal region." (PMID 41048996, 2025). "Heatmap analyses revealed that GPATCH3 expression was broadly negatively correlated with chemokines such as CXCL5 and CXCL8, as well as immunostimulatory molecules including CD40LG and TNFSF15, in a pan-cancer context." (PMID 40861452, 2025). "The ARMG risk score showed significantly positive relation with immunoinhibitors TGFB1 and VTCN1, and was negatively related with immunostimulators CD27, CD28, CD40LG, CD80, ENTPD1 and ICOS in pan-cancer." (PMID 38090588, 2023). "In most cancers, CD86, TNFSF14, KLRK1, CD48, CD40LG, CD28, C10orf54, ENTPD1, CXCL12, and POLD2 are negatively correlated (p < 0.05)." (PMID 36081989, 2022). "Lower levels of expression of CD40LG, which is expressed on the CD4+ helper T cells as a co-stimulatory molecule, are observed in cancer patients, indicating an impaired immune response." (PMID 36276933, 2022). "MANOVA on these genes reveals that this combined set of 7 genes (MYC, CD40LG, CCL4, IL7, TCF4, CCR7 and FASLG) is together statistically significantly reliant on both time post-exposure (p = 0.042) and cancer type (p < 0.001)." (PMID 33941218, 2021). "CD6, CCL19, CD40LG, XCR1, MAGEA1, ATM and CCL19 genes were significantly differentially expressed in MET-altered cancers." (PMID 33437521, 2020). "CD154 (CD40 ligand) is known to be expressed in normal lymphocytes, while recent reports have found that CD154 is expressed in various cancer cells." (PMID 23404288, 2013). "The analysis of 46 immunostimulatory genes in pan-cancer showed that HSP90B1 expression was positively correlated with CD40, CD270, PVR, MICB, ULBP1, TNFSF4, while exhibiting a negative correlation with CD48 and CD40LG in most cancers." (PMID 38243263, 2024). "CD40LG, which is the ligand of CD40, has shown great potentials in cancer therapy." (PMID 25108500, 2014). "In cancer patients, inflammatory changes indicate that IDO may be induced by soluble factors including IFNγ, TNF-α, IL-1β, soluble CD40 ligand (sCD40L) and CTLA-4 ligation to CD80/CD86 expressed by DC." (PMID 24147117, 2013). "We previously designed adenovirus AdV-D24-inducible costimulator ligand (ICOSL)-CD40L (AdV1), which selectively replicated in cancer cells but not in healthy cells and was armed with two potent costimulatory molecules: inducible costimulator ligand (ICOSL) and CD40 ligand (CD40L, CD154)." (PMID 38213479, 2023).
infectious disease (100 papers, 2004 to 2025). A disorder directly resulting from the presence and activity of a microbial, viral, or parasitic agent in humans. "Such an approach is useful to assess the role of IL-1 receptor-associated kinase-1 (IRAK1), CD40 ligand (CD40LG), C-X-C motif chemokine receptor 3, and IL13RA1 or TLR7 genes known to escape the X-related inactivation process in infectious diseases." (PMID 34367158, 2021). "Soluble CD40 ligand (sCD40L) and matrix metalloproteinase 9 (MMP-9) are inflammation markers and have been poorly described in infectious disease." (PMID 23870715, 2013).
cardiovascular disease (81 papers, 2007 to 2025). "Elevated high-sensitivity CRP (hsCRP), interleukin 6 and soluble CD40 ligand (sCD40L) levels are associated with the increased risk of cardiovascular disease." (PMID 21331754, 2011). "Soluble CD40 ligand (sCD40L) can be a marker for endothelium-related activation and a variety of cardiovascular disorders." (PMID 36923793, 2023). "CD40 ligand, which belongs to the tumor necrosis family upon engagement with the CD40 receptor, promotes atherosclerosis, which is the leading cause of cardiovascular disease." (PMID 33240706, 2020). "Platelets expressed CD40 Ligand (CD40L) is recently recognised as a key effector of cardiovascular disease development through its pro-inflammatory effect." (PMID 29514135, 2018). "It has been shown that patients suffering from cardiovascular disease exhibit increased levels of circulating and soluble CD40 ligand (sCD40L), which may influence the function of EOCs." (PMID 24358353, 2013). "So, up to now we can consider that several new nontraditional markers as CD40-CD40 ligand system and pentraxin-3 seem to be significant features of cardiovascular disease in general and in ESRD population." (PMID 22701810, 2012).
renal disease (49 papers, 2012 to 2025). "The cluster of differentiation 40 (CD40) is activated by the CD40 ligand (CD40L) in a variety of diverse cells types and regulates important processes associated with kidney disease." (PMID 33202988, 2020).
adenocarcinoma (9 papers, 1998 to 2025). A common cancer characterized by the presence of malignant glandular cells. "We report a phase 1 study of Ad-sig-hMUC1/ecdCD40L (NCT02140996), an adenoviral-vector vaccine encoding the tumour-associated antigen MUC1 linked to CD40 ligand, in patients with advanced adenocarcinoma." (PMID 36307410, 2022). "PCR and Western blot experiments conducted on four LUAD tissues and their adjacent normal lung tissues confirmed that CD40LG expression was higher in the adjacent normal tissues at both the transcript and protein levels compared to the adenocarcinoma tissues." (PMID 41048996, 2025).
genetic disorders (6 papers, 2012 to 2025). "Within the genetic disorders, so far, six genes have been implicated, coding for molecules involved in CD40 and CD40 ligand signaling (CD40 and CD40L), or in cytosine and cytidine deaminase process (AID)." (PMID 32192142, 2020).
CD40LG also shares sentences with these, for which no sentence is quoted: dengue (1,024 papers); measles (239); toxoplasmosis (219); leptospirosis (196); Hepatitis (181); influenza (163); rubella (162); ZIKV infection (156); monoclonal gammopathy (151); scrub typhus (141); Lyme disease (133); Waldenström macroglobulinemia (124); syphilis (116); bacterial infections (97); encephalitis (94); common variable immunodeficiency (88); parasitemia (88); brucellosis (68); neuropathy (67); hepatitis B (63); Q fever (63); Acute hepatitis (62); Flavivirus Infections (62); HCMV infection (61); lymphoplasmacytic lymphoma (51); multiple sclerosis (51); viral hepatitis (50); glomerulonephritis (49); cryoglobulinemia (48); Splenomegaly (47).
A further 1,144 diseases each share a sentence with CD40LG in 46 papers or fewer.